INS (insulin)
Diseases named in the same sentence as INS in open-access papers (continued):
Sharing a sentence is not in itself a finding about the gene and the disease.
Insulin resistance (continued). "Even though we measured only a selection of markers reported to be well-correlated with insulin sensitivity in LBW human and rodent subjects, we considered that other markers could potentially also contribute to the development of muscle insulin resistance." (PMID 23755234, 2013). "Non-fasting blood glucose level, serum insulin level, insulin resistance index, serum tumour necrosis factor-α (TNF-α) and serum C-reactive protein (CRP) were determined." (PMID 23717483, 2013). "Insulin resistance in the hospitalized patient is often multifactorial and one should rule out pseudo-resistance to insulin, a condition due to human or technical errors before investigating rare etiologies." (PMID 23424687, 2013). "There was no significant change in blood glucose, insulin and insulin resistance as assessed by HOMA upon ascent to 2590 m." (PMID 23936377, 2013). "Similarly, IL-6 and TNF-α have been shown to suppress insulin signaling and GLUT-4 receptor expression in skeletal muscle, both of which result in insulin resistance." (PMID 23826335, 2013). "The effectiveness of the combined therapy seems to derive from an improvement in insulin resistance and a significant lowering of the secreted insulin rather than the effect of TZD alone on T2DM." (PMID 23983807, 2013). "Our data showed significant improvements in serum FPG, insulin and in HOMA-IR after treatment with vitamin D, suggested that vitamin D supplementation could reduce insulin resistance in T2DM." (PMID 23443033, 2013). "We tested insulin resistance as the dependent variable for the same models and found neither depressive symptoms, nor perceived stress was indicative of insulin metabolism (data not shown)." (PMID 31667005, 2013). "Peripheral insulin resistance in subjects born SGA at term has been described in both children and adults, and in our children born SGA at term, we have recently reported elevated insulin and HOMA-IR values and a tendency to lower IGFBP1 after BMI adjustment." (PMID 23781317, 2013). "Indeed, the multiple post-receptor intracellular defects, such as activation of the insulin-stimulated IRS/PI3K pathway, occur in the skeletal muscles of individuals with insulin resistance." (PMID 23452929, 2013). "Suggestions have been made that not only does insulin resistance induce physiological response for MDSC and M2 macrophage expansion, but insulin may also modulate direct gene transcriptional control of these cells." (PMID 24455420, 2013). "This expected result was seen only in the healthy overweight controls, but not the matching AI, whose insulin sensitivity was on average even below the threshold of pronounced insulin resistance of <5mg·kg-1·min-1." (PMID 24146977, 2013). "Furthermore, in primary hepatocytes, KLF15 deficiency markedly inhibits activation of mTORC1 by amino acids and insulin, suggesting a mechanism by which KLF15 controls mTORC1-mediated insulin resistance." (PMID 24167585, 2013). "Interestingly, PAG significantly lowered insulin resistance in HFD obese mice evidenced by decrease fasting blood glucose and insulin, HOMA index (P<0.01), OGTT curve area (P<0.01) and ITT curve area (P<0.01)." (PMID 24058499, 2013). "After 2 hours, blood glucose levels had recuperated in both WT and S2814D mice, suggesting that S2814D mice retained insulin sensitivity and that abnormal glucose metabolism in S2814D mice was not due to peripheral insulin resistance." (PMID 23516528, 2013). "Moreover, elevated insulin and HOMA index together with low adiponectin were signs of insulin resistance." (PMID 23874450, 2013). "Similarly, resveratrol, a SIRT1 activator, enhanced insulin sensitivity in vitro in a SIRT1-dependent manner and attenuated high-fat-diet-induced insulin resistance in vivo." (PMID 23442260, 2013). "There was no fasting insulin measurement in the routine health investigation, and insulin resistance was unable to calculate." (PMID 23688357, 2013).
Insulin resistance (continued). "In this study, we found an inverse association between magnesium intake and insulin, glucose, and HOMA-IR, and that a higher level of magnesium intake from foods was protective against insulin resistance in non-diabetic participants with MetS." (PMID 24084051, 2013). "Thus taken together, overweight/obese subjects with higher circulating baseline GLP-1 have a less favourable lipid profile (higher triacylglycerols, lower HDL cholesterol) and higher insulin resistance (increased HOMA-IR, HOMA-β, and insulin)." (PMID 23566334, 2013). "Insulin resistance, however, is not uniform across the tissues of an organism and there is obvious differentiation in insulin resistance between hepatic, adipose, and muscle tissues." (PMID 24198811, 2013). "According to previous studies, we also found a negative correlation between vitamin D levels and insulin levels and insulin resistance (measured by HOMAIR)." (PMID 23509804, 2013). "5HT2C null mice have increased body weight and hepatic insulin resistance and reactivation of 5HT2C receptors specifically in POMC neurons normalizes hepatic insulin sensitivity suggesting that these specific receptors are sufficient to regulate energy and glucose homeostasis." (PMID 23550218, 2013). "Interestingly, pharmacologic administration of RBP4 and transgenic overexpression of RBP4 both induce insulin resistance in mice, while genetic deletion of RBP4 enhances insulin sensitivity." (PMID 23840311, 2013). "In vivo treatment of insulin-resistant high-fat diet (HFD)-fed C57BL/6 mice with CFE (200 mg/kg/d) for 6 weeks considerably reduced insulin resistance, glucose intolerance, plasma triacylglycerol, non-esterified fatty acids (NEFA) and LDL/VLDL cholesterol." (PMID 24265809, 2013). "HIV-infected patients had increased blood plasma insulin concentrations, increased homeostatic model assessment for insulin resistance (HOMA-IR), and increased glucose and insulin area under the curves during an oral glucose tolerance test (OGTT) compared to controls." (PMID 24303139, 2013). "Glucose: insulin ratios were significantly (P < 0.001) reduced in MHF and PLHF male offspring compared to control (CONT 2.5 ± 0.2, MHF 1.3 ± 0.1, PLHF 1.2 ± 0.1) and offspring exhibited increased insulin resistance using HOMA analysis." (PMID 23762542, 2013). "Taken into consideration the results of last data which suggest the pathophysiologic importance of hepatic insulin resistance in GDM women, the evaluation of basal insulin secretion may be a valuable metabolic parameter in these group of women." (PMID 23819910, 2013). "We are not measuring fasting glucose and insulin and will therefore not be able to estimate insulin resistance." (PMID 24152375, 2013). "Insulin resistance is a metabolic state in which insulin in physiological concentrations fails to produce a normal biologic response, and is the core perturbation in the metabolic syndrome." (PMID 23896654, 2013). "As concentrations of IRS1m decline, more insulin would be needed to account for the decrease in SIG in order to exert the same effect for stimulating glucose disposition, thus leading to the development of insulin resistance." (PMID 24312573, 2013). "An extra daily intake of 53 g milk protein but not 53 g meat increased serum insulin and insulin resistance in 8-year-old boys." (PMID 24225036, 2013). "The level of insulin sensitivity (reciprocal to insulin resistance) was statistically higher in subjects without T2DM in comparison to those with T2DM." (PMID 23349674, 2013). "Neither did replacing fasting insulin with other surrogate measures of insulin resistance, HOMA-IR (adjusted R2 = 0.55) or QUICKI (adjusted R2 = 0.56)." (PMID 24098646, 2013). "This indicates that the fasting-induced insulin resistance and hypoinsulinemia in adapted mammals is the consequence of impaired peripheral insulin signaling and not a result of pancreatic dysfunction." (PMID 23997935, 2013).
Insulin resistance (continued). "Although metabolic syndrome has been referred to as the insulin resistance syndrome, the ATPIII criteria do not include either fasting insulin level or the homeostasis model of insulin resistance (HOMA-IR)." (PMID 24228769, 2013). "In TNF-α induced insulin resistance, glucose uptake was maximally increased by rosiglitazone or insulin at 90 μM either in presence or absence of insulin." (PMID 24391675, 2013). "Because KLF15-/- mice show indications of chronic ER stress but remain insulin sensitive compared to WT littermates, we hypothesized that KLF15 may mediate ER stress-induced insulin resistance." (PMID 24167585, 2013). "UCPCR is not a replacement for established measures of insulin resistance, but is an alternative measure of fasting insulin." (PMID 24353253, 2013). "Some have shown that simvastatin had a benefit effect on insulin resistance; some have reported no benefit on insulin action, and others have identified a deterioration in glucose homoeostasis." (PMID 23671864, 2013). "Predominantly carbohydrate diets raise plasma glucose, insulin, triglycérides and non-esterified fatty acids leading to insulin resistance." (PMID 23566236, 2013). "Considering the glucose- and insulin-lowering actions of FGF19 and/or FGF21 in diabetic rodents, the potential of FGF19 and/or FGF21 treatment to ameliorate impaired glucose tolerance and insulin resistance in GDM patients warrants future attention." (PMID 24260557, 2013). "We aimed to investigate the possible effects of rs1260326 and rs1260333 on triglycerides, fasting glucose, insulin and HOMA-IR index, and estimate their effects on the risk of insulin resistance in Chinese non-diabetic children and adults population." (PMID 23383164, 2013). "In a study conducted among non-obese, non-diabetic Japanese-Americans, insulin resistance, as measured by either fasting insulin or HOMA-IR and intra-abdominal fat, were both good predictors for the 10 year incidence of MetS in sex adjusted analysis." (PMID 24086723, 2013). "AI-patients show insulin-resistance, but adequately adapted insulin secretion with higher insulin concentrations during an OGTT, because of decreased hepatic insulin extraction; this finding affects all AI-patients, regardless of dexamethasone-suppression-test outcome." (PMID 24146977, 2013). "Our study findings also indicate a significant increase (P<0.05) in serum insulin concentration, glucose and HOMA-IR index in the AZT+3TC+NVP and D4T+3TC+NVP cART regimen groups, suggesting that cART may increase insulin resistance." (PMID 23575345, 2013). "Oral hypoglycemic agents directly stimulate insulin release from β-cells to overcome insulin resistance and normalize blood glucose levels." (PMID 24137248, 2013). "In type 2 (T2) DM, primary insulin resistance, rather than defective insulin production due to β-cells destruction, seems to be the triggering alteration." (PMID 23762872, 2013). "T2D however develops when increase in insulin secretion by β cells is not able to keep pace with the increase in insulin resistance." (PMID 23308243, 2013). "It has been shown that elevation in intracellular Ca2+ may result in insulin resistance by affecting the phosphorylation of GLUT-4 and affecting insulin-mediated glucose transport and insulin secretion, leading to insulin resistance and T2D." (PMID 23538842, 2013). "In our study a significant relationship between vitamin D level with insulin level and insulin resistance was not seen." (PMID 25246913, 2012). "In summary, C‐peptide was superior to other insulin‐derived measures of insulin resistance in predicting cardiovascular and overall death in nondiabetic adults." (PMID 23316320, 2012). "All together, these findings demonstrated that nicotine enhanced insulin sensitivity in animals with or without insulin resistance, at least in part via stimulating α7-nAChR-STAT3 pathway independent of inflammation." (PMID 23251458, 2012).
Insulin resistance (continued). "Elevated oxidative stress induces insulin resistance by impairing phosphorylation of insulin receptor substrate (IRS)-1 and IRS-1-induced phosphatidylinositol 3 (PI3)-kinase activation, insulin-induced glucose uptake, and translocation of glucose transporter (GLUT)-4." (PMID 22778500, 2012). "Receiver‐operating‐curve analysis compared fasting C‐peptide against known insulin resistance measures such as fasting plasma glucose, serum insulin, HOMA‐IR, quantitative‐insulin‐sensitivity‐check‐index, and metabolic syndrome for the prediction of cardiovascular and overall death." (PMID 23316320, 2012). "The mechanism for insulin resistance is unclear, but it is thought to be secondary to viral induced adipocytokine release or HCV viral proteins directly interfering with inflammatory or muscle insulin signaling pathways." (PMID 22919404, 2012). "TZDs also decrease the gluconeogenesis from hepatic tissues, resulting in reduced insulin resistance, which leads to improved glycemic control with no enhancement in the insulin secretion." (PMID 22619731, 2012). "In differentiated 3T3-L1 adipocytes, two different OGA inhibitors have been found to increase O-GlcNAc levels but not alter insulin-stimulated phosphorylation of AKT nor induce insulin resistance either." (PMID 22536363, 2012). "As insulin resistance in new onset diabetic NOD mice is accompanied by defective in vivo insulin signaling in tissues that are targeted for glucose disposal, we examined the effects of anti-TNF-α upon insulin signaling in fat of new onset diabetic NOD mice." (PMID 22606220, 2012). "T2DM leads to glucose intolerance and insulin resistance, therefore, to evaluate changes in glucose homeostasis, the fasting and non-fasting (after glucose overload) serum glucose and insulin levels were determined at 28 and 120 days of age." (PMID 22309804, 2012). "In gestational diabetes, adipose tissue secretes low adiponectin (an anti-inflammatory and positive stimulator of insulin sensitizing) and high TNF-α and IL-6, which contribute to the inflammatory state and insulin resistance present in diabetic pregnancy as well as in macrosomia." (PMID 23227034, 2012). "The association between tertiles of triglyceride-to-HDL cholesterol ratio to fasting insulin, homeostatic model of assessment for insulin resistance (HOMA1-IR), quantitative insulin sensitivity check index (QUICKI) and glucose: insulin ratio was examined with adjustment for confounding variables." (PMID 23251403, 2012). "In our previous study, we were surprised to find that chronic nicotine treatment can significantly reduce HOMA of insulin resistance (HOMA-IR) in normal rats, suggesting that nicotine may enhance insulin sensitivity." (PMID 23251458, 2012). "There was no significant change in FBS, fasting insulin and insulin-resistance (HOMA-IR) after Ramadan fasting in the present study." (PMID 22963582, 2012). "TMS and MMS potentiated β-cell function and mass more than the control among diabetic rats; and although they did not improve peripheral insulin resistance, they did enhance hepatic insulin sensitivity in comparison to the control." (PMID 22550941, 2012). "Partial correlation analyses showed a significant negative correlation between circulating ghrelin and insulin level and insulin resistance in the entire cohort and also in men and women separately." (PMID 23029165, 2012). "To rule out the possibility of insulin resistance in TG mice, we performed insulin tolerance test (ITT)." (PMID 22384192, 2012). "Unlike Western subjects, Japanese patients with type 2 diabetes are characterized by decreased insulin secretion rather than insulin resistance." (PMID 22496878, 2012). "Such calculations when used after an oral glucose tolerance test form the basis for the Matsuda insulin resistance index, which is known to reflect peripheral, rather than hepatic, insulin sensitivity." (PMID 22844441, 2012).
Insulin resistance (continued). "The study further shows that coronary flow reserve, a measure of coronary microvessel function, is correlated to both exercise capacity and insulin resistance and supports a mediating role of CFR in explaining the link between insulin resistance and exercise intolerance." (PMID 22889317, 2012). "Since adipose tissue is a major source of lactate in insulin resistance and obesity, TZD's impact on the proliferation of small, insulin-sensitive adipocytes may explain a major portion of their impact on lactate levels." (PMID 23300538, 2012). "When β-cells are no longer able to secrete sufficient amounts of insulin to overcome insulin resistance, impaired glucose tolerance progresses to T2DM." (PMID 22364391, 2012). "Additionally, as a measure of insulin resistance we used HOMA-IR, which although highly correlated to the results of dynamic assessments of insulin function such as the hyperinsulinemic-euglycemic clamp, remains a single point static measure." (PMID 22682228, 2012). "In addition, hyperinsulinemia consistent with insulin resistance was detected in high-fat-fed male mice, whereas female mice on HFD had normal serum insulin concentrations despite a similar increase in body weight as the male mice on HFD." (PMID 23049932, 2012). "We also assessed other parameters that have been previously documented to be responsive to CR-induced changes (body composition, homeostasis model assessment-estimated insulin resistance [HOMA-IR] index, and plasma concentrations of insulin, C-peptide, adiponectin and corticosterone)." (PMID 23067400, 2012). "But, when we divided participants into 2 groups according to the presence of insulin resistance, we observed the higher TV measurements in insulin resistant group, but the difference was not statistically significant." (PMID 23231775, 2012). "Clinically, to determine the insulin resistance is critical, but detection of insulin level is invasive, and there is still no reference range for insulin resistance." (PMID 22701476, 2012). "Consistent with previous reports, T2D mice also displayed a lack of glucose response to insulin action during an insulin tolerance test - a typical feature of insulin resistance (data not shown)." (PMID 22860063, 2012). "It is interesting that the addition of the Nidd QTLs tended to further aggravate the insulin resistance, indicating that consistent with our previous report, Nidd locus influences negative impact on the insulin action." (PMID 23304119, 2012). "After only one week of HFD, significant increases in adiposity were found together with a doubling in plasma insulin despite no change in blood glucose, indicative of the development of insulin resistance." (PMID 22848500, 2012). "These techniques, including FPG, OGTT, glucose/insulin ratio, homeostasis model assessment for insulin resistance (HOMA-IR), and quantitative insulin sensitivity check index (QUICKI), are shown to correlate well with the gold standard, that is, euglycemic-hyperinsulinemic clamp." (PMID 22287962, 2012). "However, obestatin enhanced glucose uptake in either the absence or presence of insulin, promoted GLUT4 translocation, and increased Akt phosphorylation, therefore reducing insulin resistance." (PMID 23245314, 2012). "Therefore, this study was conducted to understand the ability of HCV E2 for the induction of insulin resistance and the role of HCV E2 protein in insulin signaling pathway in hepatocytes." (PMID 22721429, 2012). "In the fructose-fed hamster, a model of insulin resistance, it has been demonstrated that the intestine is not responsive to the insulin-induced downregulation of the apo B48 lipoprotein production found in the chowfed animals." (PMID 22007304, 2012). "Overexpression of SOCS3 in muscle exacerbated diet-induced obesity and insulin resistance but this effect was not due to a decreased insulin signaling but to an alteration in muscle integrity leading to a reduction in locomotor activity and energy expenditure." (PMID 23316186, 2012).